Y_RNA (Y RNA )
Gene: Miscellaneous RNA gene on chromosome 1 (173,808,489 to 173,808,622, forward strand). Ensembl gene ENSG00000252357.
Homologues: Orthologues: chimpanzee Y_RNA (100% identical), macaque Y_RNA (84% identical), mouse Gm54376 (63% identical), rat Y_RNA (63% identical), mouse Gm56322 (62% identical), rat Y_RNA (62% identical), mouse Gm54851 (61% identical). Paralogues in human: Y_RNA (74% identical), Y_RNA (70% identical), RNY1 (69% identical), RNY1P5 (69% identical), Y_RNA (69% identical), RNY1P11 (68% identical), RNY1P2 (68% identical), Y_RNA (68% identical), Y_RNA (67% identical), Y_RNA (66% identical), Y_RNA (65% identical), RNY1P10 (64% identical), and 87 more.